VIM (vimentin)
Diseases named in the same sentence as VIM in open-access papers (continued):
Sharing a sentence is not in itself a finding about the gene and the disease.
glioma (continued). "In addition, our findings demonstrated that FOXN3 over-expression triggered an obvious reduction in PCNA, CCND1, MMP9 and Vimentin expression levels in glioma cells, whereas FOXN3 ablation elicited a remarkable elevation in PCNA, CCND1, MMP9 and Vimentin expression levels." (PMID 34511432, 2021). "Furthermore, we also demonstrated that PODNL1 was essential for the expression of the mesenchymal-related biomarkers in glioma cells, evidenced by remarkably promoting of vimentin, N-cadherin, snail and fibronectin expression after PODNL1 overexpressed, and vice versa." (PMID 33033506, 2020). "Vimentin may additionally have a role in radiation induced migration of glioma cells." (PMID 31003495, 2019). "Knocking down ALG1 significantly reduced glioma cell migration and downregulated EMT-related proteins like N-cadherin, β-catenin, and Vimentin." (PMID 42002825, 2026). "This suggests that vimentin-positive gliomas may require more aggressive treatment strategies, and future research is exploring whether vimentin expression could serve as a predictive biomarker for targeted therapies aimed at inhibiting mesenchymal transition in gliomas." (PMID 40937216, 2025). "Overexpression of vimentin, alpha-smooth muscle actin (α-SMA), and twist, which are biomarkers of the mesenchymal phenotype, have been correlated with glioma progression and poor prognosis." (PMID 40724848, 2025). "Our triple staining experiment (vimentin, Iba1, GFAP) of low-grade glioma tissues showed that dExPath can reveal substantially increased colocalization between these cell type markers, with implications for the analysis of cell populations in glioma biology." (PMID 38295184, 2024). "Following the knockdown of PLAUR in glioma cells, the decreased expression of CD44 and vimentin was detected by Western blotting, while the overexpression of PLAUR via a plasmid was shown to elevate the protein level." (PMID 38398231, 2024). "Vimentin, which is high in astrocytoma and low in oligodendroglioma, can be used as a classification tool for IHD-mutant gliomas." (PMID 38067243, 2023). "We demonstrated that binding of c-Jun to VIM and UPP1 promoters is stronger in human glioma cells derived from GIV versus GII tumors." (PMID 36850002, 2023). "When GII/GIII-IDHmut gliomas were compared to GIV gliomas, significant differences of DNA methylation in the promoters of S100A2, RAB36, RIN1, UPP1, and VIM were found." (PMID 36850002, 2023). "We also conducted immunofluorescence staining for glial markers GFAP, glioma stem cell markers SOX2, tumor proliferation marker Ki-67 and invasion markers Vimentin." (PMID 37891669, 2023). "β-Sitosterol promoted E-cadherin expression and inhibited β-catenin and vimentin expressions, suggesting that β-sitosterol was involved in the EMT process and its role in the development and metastasis of glioma." (PMID 38143380, 2023). "It has been observed that FOXD2-AS1 long non-coding RNA (lncRNA) induced glioma cell proliferation and EMT by CDH1, CDH2, and VIM regulations through miR-506-5p sponging." (PMID 37051101, 2023). "NEO1 overexpression attenuated Vimentin in HCT 116 CRC cells and U87MG Glioma cells at the protein level, respectively." (PMID 36746934, 2023). "By contrast, epileptogenic gliomas display reduced expression of genes found on chromosome 10, such as the phosphatase and tensin homolog (PTEN), vimentin (VIM) and methyl guanine methyl transferase (MGMT), which are all located on 10q." (PMID 38067243, 2023). "GCL_TI specifically upregulates RG markers TNC, HOPX, PTPRZ1, and VIM, astrocyte markers CLU, LGALS1, as well as genes involved in migration and glioma network formation such as CD44, SPARC, and GAP43 (One peak)." (PMID 36823172, 2023).
glioma (continued). "A separate study will be devoted to deeply investigating the occurrence and distribution of proteins’ citrullination PTM inside pediatric brain tumors, with particular regard to VIM and GFAP peptide fragments and to glial tumors." (PMID 35328618, 2022). "Our research indicated that increasing the expression level of miR-30c can reduce the protein expression of N-cadherin and Vimentin, just as it can increase the protein expression of E-cadherin, thereby inhibiting the EMT processes of glioma cells." (PMID 36180477, 2022). "Considering that E-cadherin was not expressed in the conventional glioma cell lines except the SF767 cell, we detected the protein expression of two common EMT markers (Vimentin and ZO-1) in SHG44 and HS683 cells to investigate the EMT process in glioma." (PMID 36091778, 2022). "Using our own glioma specimens, we consistently observed significant correlations between CASZ1 protein expression and Ki‐67 and vimentin expression by IHC." (PMID 36276925, 2022). "Co-culture of mast cells with glioma cells induces the expression of serglycin, CD44, ZEB1, vimentin, CXCL10, CXCL12, and TNF-α in glioma cells and IL-6 and CXCL1 in mast cells, creating an inflammatory milieu that induce glioma cell aggressiveness." (PMID 35494005, 2022). "Considering the E-cadherin was poorly expressed in glioma cells, we tested the expression of two common EMT markers (Vimentin and N-cadherin) to analyze the EMT process of glioma." (PMID 34034744, 2021). "Specifically, gain of function of PRL1 in glioma cell lines facilitated EMT, characterized by the upregulation of N-cadherin and Vimentin, and reduction of E-cadherin levels." (PMID 35111679, 2021). "Considering the reduction in epithelial cells, E-cadherin was poorly expressed in glioma, so we tested the expression of vimentin and N-cadherin to analyze the EMT process in glioma." (PMID 33732284, 2021). "For Glioma tissue samples we screened several known biomarker proteins including ANXA1, SOD2 and VIM." (PMID 34055594, 2021). "Using western blotting, we observed that several mesenchymal markers, such as N-cadherin, Vimentin and Slug, were decreased and that an epithelial factor (E-cadherin) was increased after CUL7 depletion in gliomas." (PMID 32252802, 2020). "The tumor cells of xenografts maintained the key immune-phenotype of patient gliomas, as determined by staining using GFAP, vimentin and OLIG2." (PMID 31908598, 2020). "Another lncRNA, FOXD2 AS1, can downregulate the expression of VIM and CDH2 and upregulate the expression of E-cadherin, therefore inducing EMT in glioma." (PMID 33085646, 2020). "In keeping with our previous analysis, we noted that Cluster A, which is composed mainly of H3WT glioma cells, strongly resembles post-EMT cells and most highly expresses canonical post-EMT markers including CDH2, CDH6, and VIM." (PMID 33319914, 2020). "In the current study, IHC analysis of Vimentin and RT-PCR detection of MMP-7 showed that the expression levels of Vimentin and MMP-7 in U87 glioma cells were decreased in OAnano group, suggesting that OA impeded the migration and invasion of U87 glioma cells." (PMID 32194806, 2020). "The other three markers of vimentin, S-100 and CD34 have been studied rarely for gliomas as a single marker and frequently utilized as co-staining histological markers for differential diagnosis or prognostic prediction." (PMID 31968004, 2020). "So in the current study, we try to use radiomics features to initially identify four markers of Ki-67, vimentin, S-100 and CD34, which are histological markers recommended in several gliomas diagnosis." (PMID 31968004, 2020). "While determining the mechanisms that miR‐5188 promotes glioma progression, we confirmed that overexpression of miR‐5188 up‐regulated protein levels of CDK4, CCND1, c‐JUN, N‐cadherin and vimentin." (PMID 32902145, 2020).
glioma (continued). "And it was also upregulated in CRC, gliomas, renal cell carcinoma (RCC) tissue and indicated poor prognosis of patients with CRC and RCC, it bound miR-215 and vimentin in CRC, negatively regulating miR-342-3p in gliomas to promote proliferation and invasion." (PMID 32419983, 2020). "FOXD2-AS1 promoted glioma proliferation, invasiveness and EMT by acting as a ceRNA to sponge miR-506-5p, thus regulating the protein levels of MMP7, MMP9, N-cad, E-cad and vimentin." (PMID 33336050, 2020). "A total of 18 genes were significantly negatively correlated with DGCR5, including GNAI3, VIM, ITGB1, HIF1A, and HDAC1, all of which are critical factors affecting glioma development." (PMID 33085646, 2020). "The result of Western blot indicated that up-regulation of LINC00599 expression remarkably increased E-cadherin expression and decreased vimentin expression, which suggested that LINC00599 inhibited EMT process in glioma cells." (PMID 30867254, 2019). "Subsequently, we analyzed the expression levels of FoxM1, ADAM17 and mesenchymal markers (vimentin, YKL-40) in four glioma cell lines." (PMID 29700308, 2018). "As for β-catenin, vimentin and snail, fluorescence intensities of IKBKE-shRNA-transfected glioma cells were lower than those infected scrambled vector." (PMID 28548934, 2017). "Coaxial bioprinted tumor fibers had high expression of the glioma stem/progenitor cell biomarker Nestin, mesenchymal stem cell biomarkers CD44 and Vimentin comparing to the cells mixed in alginate hydrogel." (PMID 28469183, 2017). "Our confirmatory qPCR study showed differential gene expression levels for DPYSL2, VIM and TRIM28 in “glioma versus reference” samples." (PMID 28498803, 2017). "Based on analysis of TCGA database, we found that MTDH and mesenchymal markers are highly expressed in glioma, and MTDH expression level is positively correlated with mesenchymal marker Vimentin but negatively correlated with epithelial marker E-cadherin." (PMID 28107197, 2017). "Investigation of markers related to cancer progression in glioma cells co-cultured with MCs show a significant induction of ZEB1 and vimentin accompanied by a positive induction of glioma cell proliferation in co-culture with MCs." (PMID 28445977, 2017). "Bioinformatic analysis of genes of interest against TCGA RNA sequencing data proposed TRIM28, VIM, NAP1L1 and DPYSL2 as promising “glioma versus reference” biomarkers, and suggested CRMP1, NAP1L1, NUCL, ACTB and VIM for discrimination between GBM and LGG." (PMID 28498803, 2017). "Our data confirm that CBX7 inhibits EMT and invasion in glioma, which is manifested by influencing the expression of MMP2, MMP9, E-cadherin, N-cadherin and Vimentin in LN229, T98G cells and primary glioma cells (PGC)." (PMID 28388562, 2017). "We show that serglycin can promote aggressiveness in glioma by increasing the expression of ZEB-1 and vimentin." (PMID 28445977, 2017). "To test this we performed qPCR on a selected panel of mRNAs of importance in glioma stem cell function: CD133, nestin, vimentin, TUJ1, GFAP and MAP2." (PMID 27564115, 2016). "QRT-PCR analysis revealed a significant increase of epithelial cadherin (E-cadherin) mRNA expression and a significant decrease of mesenchymal markers N-cadherin, Vimentin, and Fibronectin expression in GANT61 treated glioma cells." (PMID 27894350, 2016). "These cells express nestin, vimentin, and SOX2 and show malignant orthotopic tumor growth, indicating that EGFRamp is serially-maintained in the glioma stem-cell-like subpopulation." (PMID 26381735, 2015). "Immunofluorescence staining of glioma cells (60th generation), assessed by laser confocal microscopy, revealed the presence of IDH1R132H, A2B5, GalC, Vimentin, GFAP, and S-100 (B1-B6)." (PMID 25879429, 2015).
glioma (continued). "In A2B5+ /CD133− SHG-139S glioma stem like cell spheres, the percentages of positive cells for IDH1R132H (C1), Nestin (C3), NG2 (C4) and Vimentin (C5) were respectively 36.77 ± 13.19%,73.86 ± 5.01%, 49.12 ± 12.83% and 73.37 ± 2.09%." (PMID 25879429, 2015). "N-cadherin and vimentin expression showed trends opposite to that of E-cadherin, suggesting that SOCE is crucial for EMT-like in glioma cells." (PMID 25433371, 2014). "In the present study, miR-211 and pM treatments decreased the expression of mesenchymal markers (e.g., N-cadherin, vimentin and β-catenin) and enhanced the expression of the epithelial marker E-cadherin, thus inducing a MET-like phenotype in glioma cells." (PMID 23183822, 2012). "These lines all grew as either stellate or bipolar cells, with some polygonal features, in monolayers, and the immunophenotypes were representative of high grade glial tumours, including expression GFAP, S100 and vimentin." (PMID 19365568, 2009). "Low-grade gliomas and well-differentiated tumors typically exhibit weak or absent vimentin staining, whereas highly invasive and mesenchymal-like gliomas show strong vimentin positivity." (PMID 40937216, 2025). "The lack of vimentin expression in oligodendrogliomas helps distinguish them from more aggressive gliomas that show mesenchymal features." (PMID 40937216, 2025). "Next, we examined vimentin and α-SMA in high-grade glioma tissue." (PMID 38295184, 2024). "Subsequent downregulation of CAV-1 decreased the levels of p-PI3K, p-AKT, N-cadherin, and Vimentin proteins in glioma cells, while increasing E-cadherin proteins, without significant effects on the total levels of PI3K and AKT." (PMID 38298655, 2024). "Over-expression of CAV-1 induced the expression of p-PI3K, p-AKT, N-cadherin and Vimentin proteins in glioma cells, while decreasing E-cadherin proteins, without significant effects on the total levels of PI3K and AKT." (PMID 38298655, 2024). "The results showed a significant reduction in the protein levels of N-cadherin and Vimentin, indicating that isocuB could inhibit EMT and thus inhibit glioma invasion." (PMID 38835342, 2024). "Additionally, glioma cluster 2 cells expressed selectins (LGALS1 and LGALS3), integrins (ITGB1), and glycosylation targets (VIM, TIMP1, HIF1A, and CD44)." (PMID 39333557, 2024). "SRGN-expressing glioma cells after co-culture with mast cells further enhance their expression of SRGN, CD44, CXCL-10, CXCL-12 and TNFα as well as EMT-related genes ZEB-1 and vimentin." (PMID 38672477, 2024). "In this study, we have shown that vimentin is overexpressed in glioblastoma tissue compared with lower grade gliomas and non-tumour brain tissue." (PMID 36765531, 2023). "Our study shows that vimentin is upregulated in glioblastoma tissue compared to lower grade glioma and non-tumour brain tissue." (PMID 36765531, 2023). "The expression of EMT markers in glioma cells was detected by Western blot and the results showed that both si-SNHG18#1 and si-SNHG18#2 enhanced the expression of E-cadherin and inhibited the expressions of N-cadherin and Vimentin." (PMID 34937497, 2022). "In addition, it has also been found that knockdown of Snail1 in glioma cells in vitro weakens the proliferation, invasion, and migration ability of GBM cells by reducing Vimentin and increasing E-cadherin expression." (PMID 35928926, 2022). "A Western blot analysis showed that E-cadherin was upregulated, but Vimentin was downregulated, in LNCTAM34A knockdown cells, thus proving that LNCTAM34A could regulate the EMT process in glioma cells." (PMID 35311131, 2022). "Furthermore, the results obtained from the Western blotting assay showed that the protein expressions of N-cadherin, Vimentin, and MMP9 were upregulated, whereas E-cadherin expression was downregulated in glioma cells treated with exosomes." (PMID 33982667, 2021).
glioma (continued). "Nitidine chloride, a natural compound extracted from the root of Zanthoxylum nitidum, exerts powerful anti-glioma effect in vitro and in vivo via the inhibition of EMT markers, including N-cadherin, vimentin, and Slug, and the phosphorylation of the ER stress marker eIF2α." (PMID 34830138, 2021). "Three immune genes related to glioma prognosis were identified as TGFB2, VIM, and TNFRSF12A." (PMID 33937046, 2021). "Regulation of vimentin and GFAP levels by pre-miR-146a are in accordance with a study wherein miR-146a overexpression increased GFAP expression and attenuated proliferation, migration and tumorigenic potential of glioma cells." (PMID 33968923, 2021). "The results showed that ME2 overexpression in SW1783 and U251MG cells upregulated the expression of N-cadherin, vimentin, YKL40, and MET expression, whereas it downregulated the expression of E-cadherin and OLIG2, suggesting that ME2 promotes PMT of glioma cells." (PMID 34381734, 2021). "In glioma, JAK2/STAT3 signaling may regulate the expression of E‐cadherin, N‐cadherin, vimentin, and β‐catenin via related transcription factors to inhibit the EMT process." (PMID 33788424, 2021). "To determine whether ME2 promotes PMT of glioma cells, we performed a western blot assay to detect the expression of MES markers MET, YKL40, N-cadherin, and vimentin; epithelial marker E-cadherin; and PN marker OLIG2." (PMID 34381734, 2021). "Moreover, the protein levels of CD44, β-catenin, N-cadherin, Vimentin, and MMP14 were also decreased in miR-124-3p overexpressing glioma cells and increased in miR-124-3p deprived cells." (PMID 32127518, 2020). "Cell morphology and expression analysis of GFAP, Vimentin, verified that TXNDC9 could regulate glioma cell differentiation." (PMID 32897242, 2020). "Furthermore, mesenchymal markers, including N‐cadherin, β‐catenin and Vimentin; the epithelial marker E‐cadherin; and upstream transcription factors, including Snail and Twist, were regulated by BACE2 in gliomas." (PMID 31856384, 2020). "We also evaluated the expression levels of the epithelial marker E- cadherin, N-cadherin, SNAI2, CD44, and vimentin in treated U87 and U251 cells to examine whether EMT is regulated by ZBC260 in glioma cells." (PMID 33093476, 2020). "Moreover, a notable reduction of Vimentin and MMP-7 was noted, which contributed to the round shape and less protrusions in U87 glioma cells after treatment, which eventually led to the disability of migration and invasion." (PMID 32194806, 2020). "Predictably, the histopathology of GDCX cells in the murine tumor was different from that of the wt-C6 murine glioma tumor; tissues stained with anti-DCX, anti-GFAP, and anti-vimentin antibodies showed a positive correlation with high DCX expression as seen in GDCX tumor." (PMID 32050972, 2020). "In this context, it was demonstrated that vimentin presents as oligomers (4–12 mers) rather than filaments at the surface of glioma cells." (PMID 33240046, 2020). "When the expression levels of E-cadherin and Vimentin proteins were measured, it was verified that observed mechanophenotypic alterations in glioma cells were not due to epithelium to mesenchymal transition." (PMID 32932941, 2020). "Phosphorylation of vimentin-Ser71 was observed in various cell types, such as glioma cells, suggesting that ROCK may have a role in the regulation of vimentin." (PMID 31888022, 2019). "This was confirmed by examination of gene expression data which showed significantly elevated median vimentin expression in GBM (p = 3.5 × 10−23) compared with normal brain and also that vimentin expression is a prognostic factor in glioma analyzed in the Rembrandt glioma database." (PMID 30987208, 2019). "As opposed to healthy glia cells, glioma generally possess increased amounts of the intermediate filaments vimentin, nestin, and GFAP." (PMID 31003495, 2019).